RDH12 (retinol dehydrogenase 12)
Diseases named in the same sentence as RDH12 in open-access papers (continued):
Sharing a sentence is not in itself a finding about the gene and the disease.
Obesity (2 papers, 2021). Accumulation of substantial excess body fat. "Finally, the proband RP-1175 with early-onset RP and obesity was solved with a homozygous missense variant p.(Leu93Pro) in RDH12 (MIM *608830) associated with non-syndromic RP." (PMID 34448047, 2021).
Atrophy (1 paper, 2021). Any weakening or degeneration, especially through lack of use. "RDH12-LCA patients have widespread RPE atrophy and fundus imaging typically shows central hypoautofluorescence corresponding to RPE cell death, surrounded by hyperautofluorescent lesions, indicating regions of high toxicity and diseased RPE." (PMID 34445569, 2021).
cataract (1 paper, 2025). Partial or complete opacity of the crystalline lens of one or both eyes that decreases visual acuity and eventually results in blindness. "In addition, 56 genes associated with ocular size, corneal defects, and cataracts were dysregulated, with 19 downregulated, suggesting a link to the hypermetropic refractive error commonly seen in RDH12 patients and associated complications seen with RP." (PMID 40365019, 2025).
cystoid macular edema (1 paper, 2023). An autosomal dominantly inherited cystoid macular edema manifesting with macular atrophy, strabismus and, sometimes, pericentral retinitis pigmentosa. "In addition, three patients had cystoid macular edema (gene groups CRB1, AIP1, and RDH12)." (PMID 37240262, 2023).
gastric cancer (1 paper, 2021). A primary or metastatic malignant neoplasm involving the stomach. "RDH12 was also one of the differentially expressed metabolism-related genes, and correlated with the prognosis of gastric cancer patients." (PMID 33717664, 2021).
glioma (1 paper, 2024). A benign or malignant brain and spinal cord tumor that arises from glial cells (astrocytes, oligodendrocytes, ependymal cells). "ADH4, DHRS3, LRAT, RDH10, RDH12, and RDH5 were higher expressed in the high-glioma-risk group while DHRS9 was lower expressed." (PMID 39465792, 2024). "Ultimately, ADH4, DHRS3, DHRS9, LRAT, RDH10, RDH12, and RDH5 were selected as prognostic genes for building an RA metabolism–related prognostic signature with glioma." (PMID 39465792, 2024). "The prognostic signature comprised of ADH4, DHRS3, DHRS9, LRAT, RDH10, RDH12, and RDH5 based on RA metabolism was established, which provided a theoretical basis and reference value for the research of glioma." (PMID 39465792, 2024). "We identified 7 promising prognostic genes (ADH4, DHRS3, DHRS9, LRAT, RDH10, RDH12, and RDH5) within glioma and developed a prognostic model with significant predictive accuracy." (PMID 39465792, 2024).
macular coloboma (1 paper, 2021). "A prior study also indicated that RDH12 mutation could lead to LCA with macular coloboma." (PMID 34130719, 2021).
Pigmentary retinopathy (1 paper, 2024). An abnormality of the retina characterized by pigment deposition. "All individuals but the youngest exhibited typical RDH12-associated widespread pigmentary retinopathy with early-onset central involvement." (PMID 38892339, 2024).
Strabismus (1 paper, 2008). A misalignment of the eyes so that the visual axes deviate from bifoveal fixation. "Mutations causing strabismus have not yet been reported, but related genes such as RDH5 and RDH12 were shown to cause fundus albipunctatus and retinal dystrophy in human, which can be accompanied by strabismus." (PMID 18836565, 2008).
retinopathies (9 papers, 2011 to 2025). "The characteristic phenotype associated with RDH12 retinopathy comprises early-onset visual loss between birth and 5 years of age (78% in the present cohort)." (PMID 22065924, 2011). "RDH12-retinopathy can be inherited both in AR and AD patterns and can be associated with wide-ranging severity, with EOSRD/LCA being the most frequently reported condition." (PMID 35491887, 2022). "In order to study the disease mechanisms and screen potential therapeutics for RDH12-retinopathies, three mutant RDH12 stable HEK-293 cell lines were created; two expressing missense mutations (p.Y226C and p.A109P) and one nonsense mutation (p.S13*)." (PMID 34445569, 2021). "RDH12 retinopathy is characterized by impaired visual function starting at 2–4 years, generally, which is inconsistent with the finding in our study." (PMID 34567070, 2021). "Drugs with ER stress lowering properties, in addition to antioxidants and retinal scavengers, represent a new class of potential drugs that can be targeted for RDH12-related retinopathies." (PMID 34445569, 2021). "Understanding the molecular pathogenesis of RDH12-related retinopathies will enable the identification of therapeutic targets and development of novel therapies." (PMID 34216980, 2021). "In conclusion, two human iPSCs lines were generated from patients with RDH12-related retinopathies." (PMID 34216980, 2021). "If successful, these may also be effective for RDH12-retinopathy." (PMID 35491887, 2022). "A phenotypic feature of RDH12 retinopathy is sparing of the peripapillary region, pathognomonic of ABCA4-retinopathy." (PMID 35162940, 2022). "There are currently no treatments available for RDH12-related retinopathies, and little is known about the disease mechanisms." (PMID 34445569, 2021). "Future directions: There is currently no treatment available for RDH12-retinopathy." (PMID 35491887, 2022). "However, owing to the lack of phenotype observed in the Rdh12-/- mouse models, the exact disease mechanism of RDH12-retinopathies is not known." (PMID 34445569, 2021).
tumor (7 papers, 2013 to 2025). "CCR4, CMA1, ADCY1, RDH12, and ENTPD2 exhibited higher expression levels in the low-risk group, indicating their possible tumor-suppressive functions." (PMID 40243888, 2025).
cancer (4 papers, 2013 to 2024). A tumor composed of atypical neoplastic, often pleomorphic cells that invade other tissues. "Cancer-associated protein alterations such as upregulation of peroxiredoxin-1, annexin 5, and iNOS, and downregulation of RDH12, retinaldehyde dehydrogenase 1, SOD1, and MYL 9, were found in the EC tissues of the diabetic group." (PMID 35454982, 2022). "Alterations in the proteins that are usually associated with cancer, including the upregulation of peroxiredoxin-1, annexin 5, and iNOS, and down-regulation of RDH12, retinaldehyde dehydrogenase 1, SOD1, and MYL 9, were found in the EC tissues of the diabetic group." (PMID 35454982, 2022). "When comparing RM with PC, we identified key regeneration-related genes APOD and IBSP, along with several significant pathways: cAMP signaling pathway (HHIP), cytokine-cytokine receptor interaction (IL17D), pathways in cancer (HHIP, DAPK2), and biosynthesis of cofactors (RDH12, HAAO)." (PMID 39684926, 2024). "In the IHC data of HPA, there is a lack of carcinoma or corresponding normal tissues of several candidate genes includingSDR9C7,RDH12,RAET1E,CERS3,PLA2G4E,CYP4F22, andDENND2C." (PMID 36017889, 2022).
metabolic disorders (1 paper, 2024). "Those chronic disorders were related to metabolic disorders and congenital anomalies coded by AGTX, GALC, GRHPR, RDH12, and RPGRIP1L." (PMID 38553482, 2024).
RDH12 also shares sentences with these, for which no sentence is quoted: Macular dystrophy (5 papers); Leber congenital amaurosis 13 (4); Stargardt disease (4); autosomal dominant retinitis pigmentosa (3); Nystagmus (3); epilepsy (2); myopia (2); albinism (1); Alzheimer disease (1); amblyopia (1); Andersen-Tawil syndrome (1); Anxiety (1); Blindness (1); cervical squamous cell carcinoma (1); ciliopathies (1); clear cell renal cell carcinoma (1); congenital stationary night blindness (1); glomerulonephritis (1); hyperopia (1); lung carcinoma (1); maternally-inherited diabetes and deafness (1); Onset (1); short QT syndrome (1); Usher syndrome (1).